IFI16 (interferon gamma inducible protein 16)
Diseases named in the same sentence as IFI16 in open-access papers (continued):
Sharing a sentence is not in itself a finding about the gene and the disease.
tumor (continued). "First, the expression of IFI16 was analyzed with tumor stage for HNSCC." (PMID 32577124, 2020). "Furthermore, DHA regulates the crosstalk between autophagy and IFI16/caspase-1 inflammasome, which inhibits IL-1β production in tumor microenvironment." (PMID 32577124, 2020). "p204, a murine member of the interferon-inducible p200 protein family, and its human analogue, IFI16, have been shown to function as tumor suppressors in vitro, but the molecular events involved, in particular in vivo, remain unclear." (PMID 29691417, 2018). "Importantly, the re-expression of IFI16 orthologs in immunocompetent mice abrogates tumorigenesis and activates anti-tumor immunity, indicating that early epigenetic changes may influence tumorigenesis by targeting co-located genes." (PMID 40386782, 2025). "Notably, clinical observations reveal reduced IFI16 expression levels in BC tissues, reinforcing its crucial role as a tumor suppressor intriguing DNA-binding capability of the IFI16 protein towards ssDNA and cruciform structures emerges as a pivotal aspect in its tumor suppressive functions." (PMID 40386782, 2025). "However, the mechanism of IFI16 action in tumor formation is still unclear." (PMID 33659024, 2021). "The role of IFI16 in mediating change in the tumor microenvironment remains unknown." (PMID 34150748, 2021). "However, in our study, when we measured the markers of TAMs, including HIF-1α, CCL2, and PECAM1, we found that gemcitabine treatment potently activated the expression of TAM markers, while knockdown of IFI16 reversed the increase in TAMs in the tumor microenvironment." (PMID 34150748, 2021). "Moreover, depletion of TAMs attenuated IFI16-induced PAAD tumor growth." (PMID 34150748, 2021). "Additionally, knockdown of IFI16 could significantly potentiate gemcitabine treatment in PAAD, which may be associated with the reduced infiltration of TAMs in the tumor microenvironment." (PMID 34150748, 2021). "However, ICP0 is not necessary or sufficient for the loss of IFI16 in a tumor-derived cell line, and the ICP0-independent loss of IFI16 in HeLa cells is dependent in part on VHS RNase activity." (PMID 32430029, 2020). "Therefore, our findings demonstrate that DHA may act as a RalB inhibitor to regulate the crosstalk between autophagy and IFI16/caspase-1 inflammasome, which inhibits IL-1β production in tumor microenvironment." (PMID 32577124, 2020). "Although, these observations suggest that increased levels of IFI16 protein negative regulate the expression of c-MYC in certain tumor cell lines, it remains unknown how increased levels of the IFI16 protein in human normal cells contribute to cellular senescence-associated cell growth arrest." (PMID 20052289, 2010). "IFI16 expression is significantly downregulated in HCC tissues, highlighting its potential role as a tumor suppressor." (PMID 40386782, 2025). "Elevated levels of IFI16 have been observed to positively correlate with several key clinicopathological features of RCC, including lymphatic metastasis, tumor stage, and histopathological grade." (PMID 40386782, 2025).
tumor (continued). "More recent insights have unveiled a novel facet of IFI16/Ifi202 within TME, where it triggers tumor-promoting inflammation, thereby contributing to the formation of an immunosuppressive TME in BC." (PMID 40386782, 2025). "Subsequent to this, our discussion centers on the diverse roles of AIM2, IFI16, IFIX, and MNDA, providing a comprehensive elucidation regarding their functions and mechanisms across various tumor types." (PMID 40386782, 2025). "TNFα and IFNβ are also released upon activation of IFI16, which was elevated in the HPV16-related OPSCC tumor model compared to other models." (PMID 41401057, 2025). "By suppressing Wnt/β-catenin signaling, IFI16 prevents the transcriptional activation of EMT-inducing genes, thereby maintaining epithelial characteristics and reducing tumor aggressiveness." (PMID 40386782, 2025). "For instance, IFIT1, IFIT3, IFI-16, ISG15, MX1, and OAS1 have been shown to have tumor-suppressive function." (PMID 40563638, 2025). "The 11 coupregulated factors included PTPRC (a positive regulator of T-cell activation), IFI16 (a hematopoietic differentiation modulator), and SMARCE1 (a chromatin remodeler that enhances tumor suppressor accessibility)." (PMID 41304891, 2025). "In summary, IFI16 exerts its effects by modulating IL6, which activates the IL6/PI3K/AKT pathway, promoting the occurrence of ccRCC EMT, and ultimately enhancing tumor proliferation and metastasis." (PMID 38831470, 2024). "Substantial CNV deletions were observed in PABPC5, MSH6, IFI16, GNS, ERCC4, BRCA1 and ACACB, while substantial CNV amplification was observed in most tumour types for the remaining genes." (PMID 37660060, 2023). "The result showed that IFI16 also increased in most of ESCC cells lines and ESCC tumor compared with immortalized esophageal cells (HET1A and NE2) and non-tumor tissue." (PMID 35371314, 2022). "To evaluate the significance of IFI16 in ESCC development, we also detected the IFI16 proteins levels in different ESCC cell lines and ESCC tumor tissues by western blot." (PMID 35371314, 2022). "Overexpression of IFI16 significantly promoted the orthotopic growth of PAAD tumors in a murine model and altered the immune cell profile in the tumor microenvironment by increasing the TAM population." (PMID 34150748, 2021). "It is possible that the IFI16-overexpressing TAM population is a heterogenic population that contains the M1 and M2 phenotypes of macrophages, which both contribute to the tumor growth of PAAD." (PMID 34150748, 2021). "Although AIM2 was thought to be a tumor suppressor, overexpression of AIM2 and IFI16 synergistically promotes OSCC cell growth and prevents apoptosis via activating NF-κB pathway, which suggests the oncogenic potential of AIM2 and IFI16 in OSCC." (PMID 32903550, 2020). "The mRNA expression of cGAS-STING pathway members, except for IFI16 and NLRC3, was significantly related with individual cancer stages and tumor grades in HCC." (PMID 33006365, 2020). "Additionally, RRM1 inhibition enhances DAC-mediated tumor suppressor gene reactivation and STING pathway activation via DNA damage-induced IFI16 sensing." (PMID 41748545, 2026). "Similar colocalization of IFI16 and LANA was also observed in KS tumor skin biopsies." (PMID 39927772, 2025). "IFI16 and HBGEF are growth condition selective regulators, suggesting that these genes might be explored as markers of GBM cells responding to the tumor microenvironment in future independent work." (PMID 40683881, 2025). "In 2022, researchers demonstrated that inhibition of EZH2 and HDAC could reactivate IFI16-directed immune response of HER2-positive BC patients, changing “cold tumor” into “hot tumor”, and sensitizing anti-HER2 treatment responses." (PMID 37803297, 2023). "Moreover, interferon gamma-inducible protein 16 (IFI16) is degraded by soluble E7 antigen and as a result IFN-γ decreases in the tumor microenvironment." (PMID 35632488, 2022).
tumor (continued). "Injection of liposome PBS had minimal effect on the IFI16 overexpression-induced PAAD tumor growth and progression, suggesting that no vehicle effect was observed." (PMID 34150748, 2021). "Altogether, ICP0 seems to play the major role for IFI16 degradation in non-cancerous human cell lines, while HSV-1 vhs-mediated IFI16 mRNA destabilization seems dominant in tumor-derived cells." (PMID 33353088, 2020). "Moreover, the IFI16-induced inflammasome was found to inhibit HCC growth and metastasis, and was a tumor suppressor during the development." (PMID 33006365, 2020). "IFI16 plays an important role in virus restriction, however, its role in tumor setting is not well studied." (PMID 31949493, 2020). "Notably, the nuclear‐specific localization of IFI16 may enable it to escape the classic STING‐dependent DNA damage response mode and instead reshape the tumour microenvironment through a non‐classical NF‐κB pathway." (PMID 40770819, 2025). "This clinical paradox suggests that extracellular IFI16 may execute non-canonical biological functions distinct from its established nuclear tumor-suppressive mechanisms." (PMID 40386782, 2025). "Additionally, IFI16 has been shown to suppress the activation of other inflammasomes, such as AIM2 and NLRP3, thereby modulating inflammatory responses in a way that can either promote or inhibit tumor progression depending on the context." (PMID 40386782, 2025). "This group includes interferon-inducible protein 16 (IFI16), myeloid cell nuclear differentiation antigen (MNDA), absent in melanoma 2 (AIM2), and pyrin and HIN domain family member 1 (PYHIN1), each of which has been reported to be related to tumor progression." (PMID 37998338, 2023). "Interestingly, we observed that gemcitabine treatment could induce TAM population in the tumor microenvironment of orthotopic PAAD and that knockdown of IFI16 could significantly abolish the increase in the TAM population." (PMID 34150748, 2021). "Interestingly, studies have previously reported the tumor-suppressive activity of AIM2 and IFI16." (PMID 32328125, 2020). "These interactions may point to mechanisms by which IFI16 and MNDA could act as tumor suppressors." (PMID 25665578, 2015). "Patients with p16 negative tumor exhibited worse survival rate regardless of IFI16 status." (PMID 23956879, 2013). "Patients with p16 negative tumor exhibited worse prognosis regardless of whether IFI16 was positive (P = 0.046) or negative (nonsignificant, P = 0.157)." (PMID 23956879, 2013). "The expression of IFI16 was further examined in two datasets of human PAAD samples, which revealed that IFI16 was significantly overexpressed in tumor tissues than in non-tumor adjacent tissues in both datasets." (PMID 34150748, 2021). "In tumor-derived cell lines, ICP0 seems neither sufficient nor required for IFI16 degradation during HSV-1 infection." (PMID 33353088, 2020).
cancer (34 papers, 2010 to 2025). A tumor composed of atypical neoplastic, often pleomorphic cells that invade other tissues. "Of the IFN-γ-related genes, IFI16 was upregulated >150-fold at baseline in BRCA1-mutated cancer cells." (PMID 31840082, 2019). "Although we cannot fully conclude the mechanisms of IFI16 upregulation by gemcitabine treatment, it is postulated that gemcitabine, as a DNA damage agent, may cause the breakdown of dsDNA in both normal and cancer cells in the tumors." (PMID 34150748, 2021). "Therefore, it is likely that alterations (increases or decreases) in the expression of IFI16 protein in certain individuals contribute to increased susceptibility to premature aging and aging-dependent cancers." (PMID 20052289, 2010). "Additionally, our findings also indicate that the loss of IFI16 expression, as found in certain cancers, may provide a survival advantage to cancer cells in microenvironments with low glucose levels." (PMID 21573174, 2011). "Experimental knockdown of IFI16 reduces PD-L1 levels and suppresses cancer cell proliferation, migration, and invasion in both in vitro and in vivo models." (PMID 39949780, 2025). "Previous studies have indicated that IFI16 plays diverse roles in the development of various cancers." (PMID 38831470, 2024). "Targeting the IFI16 pathway in cancer therapy offers potential avenues for enhancing immune responses against tumors and overcoming resistance to existing treatments." (PMID 38523155, 2024). "The IFI16 protein contributes to B-cell differentiation, which was shown to serve as a prognostic factor for many types of cancers and is involved in immune invasion." (PMID 39534570, 2024). "To further assess the expression of IFI16 in ccRCC, we performed IHC on cancer tissues and paired adjacent normal tissues from 92 ccRCC patients collected at our institution." (PMID 38831470, 2024). "In this study, we used the UALCAN database to analyze the expression of IFI16 in ccRCC patients and found that IFI16 was highly expressed in cancer tissues compared to normal tissues." (PMID 33659024, 2021). "Our study also found that DHA reduced the expression level of IFI16 in three human cancer cells of Hep-2, Cal-27, and HeLa." (PMID 32577124, 2020). "In concordance with this idea, it was found that the blockage of autophagy potentiated the activity of IFI16 inflammasome, whereas the stimulation of autophagy limited its activity in three human cancer cells of Hep-2, Cal-27, and HeLa." (PMID 32577124, 2020). "Altogether, these results indicated that the exposure to DHA triggered autophagy, which limited the IFI16 inflammasomes in cancer cells." (PMID 32577124, 2020). "These genes included ANKLD1, AXL, CAV1/2, LDHB, ETS1, IFI16, PTRF (cavin), KIAA1199 and VIM, which have previously been linked to drug resistance in breast and other cancers." (PMID 26646320, 2016). "In addition to NLRP3 being implicated in chronic inflammation and cancer progression, the dsDNA-sensing PRRs, AIM2 and IFI16, have been involved in oral diseases and cancer." (PMID 41440367, 2025). "The function of IFI16 in various cancers exhibits a dual nature." (PMID 39744568, 2025). "Recent research suggests that IFI16 also plays an important role in cancer." (PMID 38831470, 2024). "Further study is required to determine whether IL18 suppresses or promotes cancer development through Ifi16." (PMID 38139000, 2023). "Another study reported that Ifi16 promoted cancer development in vitro and in vivo." (PMID 38139000, 2023).
cancer (continued). "Synthesizing our findings with those of other studies, it seems likely that various molecules might contribute to the malignancy of cancer through the increased expression of IFI16." (PMID 37998338, 2023). "The relationship between IFI16 and cancer progression has been elucidated via several mechanisms." (PMID 37998338, 2023). "The interaction signals were detected in cancer-associated adipocytes, but not in BC cells, probably due to the low expression of IFI16 in luminal-type BC cells." (PMID 35593921, 2022). "Contradictory data regarding the role of IFI16 in cancer has been reported in the literature." (PMID 28611294, 2017). "Therefore, further studies will be needed to examine the role of IFI16 protein in the energetic-stress-induced metabolic pathways, autophagy, cell survival, and the development of cancers." (PMID 21573174, 2011). "However, the IFI16-STING axis may play a pro-cancer role in the context of cancers induced by oncogenic viruses." (PMID 38139802, 2023). "In human cancers, the role of IFI16 may be far from conclusive." (PMID 34150748, 2021). "Collectively, the findings from this research endeavor offer a fresh perspective on the functional role of IFI16 in the pathogenesis of CRC, particularly through its modulation of cancer cell proliferation." (PMID 40386782, 2025). "Apart from BIRC5, GMIP, IFI16, and TCIRG1, other genes didn’t show significant differences in individual cancer stages." (PMID 35237298, 2021). "As shown in the pan-cancer view, the 4 hub genes (IFI16, LMNB1, RHBDF2, and TACC3) were significantly up-regulated in ccRCC samples and other cancer types when compared to adjacent normal tissues (p < 0.001)." (PMID 33796525, 2021). "Induced ZNF395 expression led to the upregulation of genes known to play a role in cancer as well as a subset of interferon (IFN)-stimulated genes (ISG) involved in antiviral responses such as IFIT1/ISG56, IFI44 and IFI16." (PMID 24086395, 2013). "IFI16 interferes with ATM activity, which is required for cancer cell fitness; thus, it stands to reason that IFI16 may additionally be lactylated during cancers." (PMID 39772686, 2025). "Furthermore, emerging evidence suggests that IFI16 promotes ESCC metastasis by upregulating the expression of fibroblast growth factor (FGF) proteins, which are known to play crucial roles in cancer cell migration, invasion, and angiogenesis." (PMID 40386782, 2025). "As for other genes involved in dsDNA/dsRNA/ssRNA sensing like CGAS, RIG-I, MAVS, DDX41, and IFI16, whose expression in either cancer cells or other cell types, were not significantly impacted by redox status of any cell types." (PMID 41378285, 2025). "Recent studies suggest that DNA sensors such as AIM2, TLR9, DHX9, DHX36 and adaptor STING may have roles in CRC development, and the other DNA sensors such as DDX41, DDX60, IFI16, and DAI participate in the development of other types of cancers." (PMID 31949493, 2020). "And it was found that IFI16 and AIM2 were significantly upregulated in the patients with cancer." (PMID 32577124, 2020). "Intriguingly, the expression levels of IFI16 did not display any statistically significant association with the infiltration of CD8+ TILs or the expression of PD-L1, implying that its impact on cancer progression may be independent of these immunological factors." (PMID 40386782, 2025).
bacterial infections (2 papers, 2019 to 2025). "IFI204/IFI16 is also implicated in sensing intracellular bacterial infection." (PMID 30936875, 2019). "Hence, IFI204/IFI16 is implicated in sensing intracellular bacterial infection." (PMID 30936875, 2019). "Evidence shows IFI16/IFI204-mediated inflammasome activation via bacterial infections, like Campylobacter concisus, and via viral pathogens, such as KSHV and HIV." (PMID 41304242, 2025). "Knockdown of IFI204/IFI16 by small interfering RNA significantly inhibited IFN-β release in response to intracellular bacterial infections such as Francisella novicida, Listeria monocytogenes, Mycobacterium bovis." (PMID 30936875, 2019). "In contrast to the extensive studies of IFI204/IFI16-mediated response to viral and intracellular bacterial infections through gene knockdown in vitro, there is little knowledge regarding the role of IFI204/IFI16 in response to extracellular bacterial infection." (PMID 30936875, 2019).